RNU6-1272P (RNA, U6 small nuclear 1272, pseudogene)
Gene: Small nuclear RNA gene on chromosome 7 (138,876,359 to 138,876,465, reverse strand). Ensembl gene ENSG00000199646.
Homologues: Orthologues: chimpanzee U6 (99% identical), macaque U6 (93% identical), pig U6 (76% identical). Paralogues in human: RNU6-41P (87% identical), RNU6-1019P (85% identical), RNU6-1060P (85% identical), RNU6-116P (85% identical), RNU6-1251P (85% identical), RNU6-12P (85% identical), RNU6-13P (85% identical), RNU6-166P (85% identical), RNU6-22P (85% identical), RNU6-25P (85% identical), RNU6-32P (85% identical), RNU6-33P (85% identical), and 1286 more.